LEP (leptin)
Diseases named in the same sentence as LEP in open-access papers (continued):
Sharing a sentence is not in itself a finding about the gene and the disease.
tumor (continued). "Epithelial mesenchymal transition (EMT) plays an important role in the development of tumor by enhancing invasion ability, which worsen the prognosis of tumors, and leptin plays a key role in this process." (PMID 34485124, 2021). "In in vivo experiments, tumor-bearing mouse models showed that leptin increased the volume of tumors and promoted lung metastasis." (PMID 33842335, 2021). "Briefly, our findings suggest a strong suppression of CYP19 gene expression in the tumor tissue during treatment with exemestane even in women with elevated leptin levels." (PMID 34554372, 2021). "Leptin is the primary adipokine secreted by adipocytes and activates the proliferation and migration of tumor cells." (PMID 34202411, 2021). "In the tumor microenvironment, adipocytes show an extensively reprogrammed metabolic phenotype, characterized by increased lipolysis and secretion of leptin, TNF-α, and IL-6, but decreased production of adiponectin." (PMID 33535537, 2021). "In this way, leptin induces metabolic reprogramming in T cells, and tumor-infiltrating T cells bear its receptor." (PMID 34868066, 2021). "We also found that the serum leptin levels in EE mice decreased even after radiation exposure, and we anticipated that the inhibitory effect of EE on tumor growth would continue even after radiation exposure." (PMID 34745135, 2021). "In tumor samples, leptin is overexpressed in luminal B and triple-negative carcinomas (p = 0.0046), whereas ObR is found to be overexpressed in luminal B tumors (p = 0.0425)." (PMID 33644151, 2021). "Experimental studies suggested that inhibition of leptin or IL-6-JAK/STAT3 signaling in CRPC-cells enhances the anti-tumor NKCC via alteration of PD-L1/NKG2D-ligands levels." (PMID 34830209, 2021). "EE is also known to reduce leptin secreted from white adipose tissue, thereby suppressing tumor growth." (PMID 34745135, 2021). "Third, LEP mRNA levels in tumor tissue are much lower (1/12th) than those in adipose tissue (data not shown)." (PMID 34414945, 2021). "The methylation profiles of LEP were measured in 63 formalin-fixed, paraffin-embedded tumor tissues by quantitative polymerase chain reaction using a MethyLight assay." (PMID 34884678, 2021). "Taken together, these results indicated that high levels of serum leptin and pSTAT3/CEBPD/MCL1 axis activation were significantly associated with advanced clinical stages and tumor grades." (PMID 34156978, 2021). "Here, we investigated the diagnostic accuracy of selected tumor biomarkers (i.e., AFP, PIVKA-II and GPC-3); adipokines (i.e., adiponectin and leptin) and IL-6, alone or in combination, for the discrimination between patients with or without NAFLD-related HCC." (PMID 34064999, 2021). "The leptin gene expression was negatively correlated with the infiltration of tumor-reactive CD8+ T cells in human TNBC tumors from obese patients when compared to non-obese." (PMID 34350120, 2021). "Serum leptin levels on day seven were correlated significantly to sex (p = 0.004), distant metastases (p = 0.019), patients’ BMI (p = 0.002), tumour grade (p = 0.033) and serum CRP levels on day one (p = 0.027)." (PMID 34827598, 2021). "Various mechanisms such as altering hormones (androgen, IGF-1, insulin, circulating, and leptin) reduced tumor volume, and reformed antioxidative defense and immune care." (PMID 33927639, 2021). "GRO-α, IL-1β, Oncostatin-M and Leptin, all linked to tumor growth and inflammation, were significantly altered in the IORT group: Leptin increased; GRO-α, IL-1β, oncostatin-M decreased." (PMID 33946741, 2021). "Through its impact on the immune system, secretion of leptin by ASCs impacts not only neoplastic cells, but also the resident tumor microenvironment." (PMID 34912237, 2021). "The first leptin peptide analogues with antagonistic activity towards leptin receptor and efficient anti-tumor activity in breast cancer were designed based on leptin binding sites II and I." (PMID 34356668, 2021).
tumor (continued). "Most of these clinicopathological factors have already been identified as related to serum levels of leptin or higher leptin expression in the tumour cells." (PMID 34827598, 2021). "This is highlighted by the gastrocnemius leptin decrease and the tumour oxidative and inflammatory status changes." (PMID 32472095, 2020). "Leptin, visfatin and adiponectin play a role in the regulation of inflammation, tumor microenvironment and progression of hepatic diseses." (PMID 32212784, 2020). "Leptin and its receptors (ObR) are highly expressed in CRC, indeed, leptin inhibition reduces tumor growth and leads to an overexpression of ObR, which inhibits 5-FU-induced apoptosis." (PMID 33396628, 2020). "When BC cell lines cocultured with mature adipocytes, adipocyte-derived leptin and IL-6 promoted local invasion and eventually metastasis of tumor cells via activation of lysyl hydroxylase 2 (PLOD2)." (PMID 32787888, 2020). "In summary, the JAK/STAT signaling pathway of Leptin can exert a critical role in tumor proliferation, apoptosis, and angiogenesis." (PMID 33746736, 2020). "As regards the tumour microenvironment within the mammary gland, leptin can modify the tumour to modulate migration of endothelial cells, angiogenesis, macrophage phenotypes and functions, and recruitment of monocytes and neutrophils." (PMID 32033341, 2020). "In tumor cells and within the tumor microenvironment, the over-expression of leptin and its receptor, ObR, promotes proliferation and the EMT activation program, a biological process that promotes invasion and metastasis." (PMID 33334030, 2020). "Delivery of an engineered oncolytic vaccinia virus expressing recombinant leptin improved the anti-tumor function and memory response by TILs through enhanced mitochondrial oxidative metabolism." (PMID 32642279, 2020). "Studies have shown that Leptin can promote tumor cell proliferation, inhibit tumor cell apoptosis, and promote tumor angiogenesis." (PMID 33746736, 2020). "We evaluated the effect of leptin as a promoter of EMT in the MCF10A non-tumor mammary epithelial cell line." (PMID 33334030, 2020). "In parallel, leptin, an important pro-carcinogenesis adipokine, is strongly captured by tumour cells because it promotes cell proliferation by activating main signalling pathways such as JNK, AKT, p385." (PMID 32472095, 2020). "Data of the present study reflect that both proliferation and apoptosis occur in cells of the tumor and they are controlled via leptin and adiponectin together with PLC, Raf, and ERK." (PMID 32455738, 2020). "Intriguingly, high leptin expression was an indicator of favorable tumor features and better survival in CRC patients." (PMID 33167521, 2020). "With their in vivo study, the authors showed that, in the bone microenvironment, leptin enhanced sICAM-1 production by tumour cells and induced bone erosion." (PMID 32033341, 2020). "Cao and colleagues showed that leptin, by triggering M2 macrophage-related cytokine IL-18 production, contributes to tumour progression and the development of metastasis." (PMID 32033341, 2020). "Leptin is another adipokine important in tumor progression and secretion of leptin is increased in CAAs compared to mature adipocytes." (PMID 33339340, 2020). "Previous studies described leptin as a tumor metastasis-promoting factor that induces inflammation and epithelial–mesenchymal transition (EMT), mostly in malignant breast and lung cancers." (PMID 33255835, 2020). "Obese nude mice bore larger tumor xenografts than lean animals, and were hyperglycemic and hyperinsulinemic with an elevated level of leptin and visfatin in sera, and also were accompanied by a fatty liver." (PMID 33381605, 2020). "Obese mice treated with anti-PD1 have shown greater tumor response compared to lean controls, potentially due to leptin-induced expression of PD1." (PMID 32244756, 2020).
tumor (continued). "Leptin signaling was also shown to be involved in the promotion of a stem-like phenotype related to resistance to therapy and tumor recurrence and metastasis." (PMID 32120856, 2020). "Since TGF-β has shown to induce autophagy in several tumor types, we employed RT-qPCR and ELISA to examine its expression in both control and leptin-treated MSCs." (PMID 32289750, 2020). "In in vitro, in vivo, and patient studies have demonstrated that leptin is an actor in the induction of EMT during tumor progression; however, the question remains: What is the mechanism for the activation of this process?" (PMID 33334030, 2020). "Signal of similar intensity as in respective control, either for leptin or for adiponectin was found in each of the cells of the tumor." (PMID 32455738, 2020). "Aspirin has been found to inhibit tumor growth in obese mice through lowered plasma glucose, insulin, leptin, WBC, neutrophils, lymphocytes, soluble P-selectin, TGF-β1, and glutamine." (PMID 32121098, 2020). "Our results showed that despite regular physical activity, the amount of adipose tissue plays a very strong role in tumour development, particularly through adipokine production (adiponectin, leptin)." (PMID 32472095, 2020). "Aspirin mitigated tumor growth in obese mice with lowered glucose, insulin, leptin, leukocyte number, glutamine, TGF-β1, and platelet activation." (PMID 32121098, 2020). "Leptin is a key paracrine mediator regulating the interaction between stromal cells and BC cells in the meaning of tumor metabolism." (PMID 32120856, 2020). "Rosiglitazone was also able to prevent the leptin-induced tumor growth in nude mice after 12 weeks of treatment." (PMID 32937951, 2020). "It is noteworthy that leptin/ObR were co-expressed with associated signaling pathway markers such as STAT3 and Akt, which in turn are involved in tumor progression and invasion." (PMID 33316976, 2020). "Leptin can induce the expression of vascular endothelial growth factor and promote neovascularization in tumor tissue." (PMID 32819324, 2020). "Multiple factors in tumor tissue, including leptin expression, can promote aggressive phenotypes and tumor metastasis by promoting EMT." (PMID 32836215, 2020). "Tumour tissue expression of leptin and/or of Ob-R has been found to correlate with aggressive tumour behaviour." (PMID 32033341, 2020). "In all, the effects of FAO and leptin on anti-tumor CD8+ T cell function are complex and likely dependent on many environmental factors, and further studies are needed to delineate these." (PMID 33170123, 2020). "Leptin is an adipokine whose synthesis is positively correlated with the BMI and is mainly produced by adipose cells but also by epithelial tumor cells and cells in the microenvironment, such as fibroblasts." (PMID 33505957, 2020). "In this regard, the present data strongly suggest that the tumor-promoting capacity of leptin, and its facilitatory role in the onset of chemoresistance, are linked to its ability to promote autophagy in OS cells by upregulating TGF-β in tumor-associated MSCs." (PMID 32289750, 2020). "Viral-mediated leptin overexpression in tumor cells promotes T cell activation and antitumor immunity, which has exceeded that achieved by oncolytic virus alone." (PMID 32244756, 2020). "Results show that leptin signaling increases the expression of tumor progression and chemoresistance-related genes (ABCB1, WNT4, ADHFE1, TBC1D3, LL22NC03, RDH5, ITGB3) in TNBC cells." (PMID 32471192, 2020). "In a different study, metabolic dysfunction of TILs was overcome by elevating leptin levels in the tumor microenvironment." (PMID 32642279, 2020). "The ObR antagonist, Allo-aca, a short leptin-based peptidomimetic inhibits leptin induced tumor cell proliferation and angiogenesis." (PMID 33339340, 2020).
tumor (continued). "The increased levels of adipose tissue-derived factors, such as TNF-α, IL-6, IL-8, macrophage chemoattractant protein (MCP-1), and leptin, and their role in tumor progression have been well-documented." (PMID 32847136, 2020). "Recently, a possible interconnection between leptin and the Notch pathway, which is responsible for transformation, proliferation, tumor progression, EMT and chemoresistance, was described." (PMID 33101198, 2020). "The different tissues changed their signalling pathways and adipokine/cytokine secretions, such as adiponectin and leptin, resulting in a decrease in anti-oxidative response and inflammation in the tumour environment." (PMID 32472095, 2020). "This fluctuation shows we still have much to uncover about the role leptin plays within our bodies and in the progression of tumor growth." (PMID 32742493, 2020). "We illustrated the mechanism of WCAF and discovered that its anti-tumor activity in colorectal cancer is mediated by Leptin/STAT3/VEGF signaling and its interaction with the anti-angiogenic agent BEV." (PMID 33746736, 2020). "Leptin and adiponectin released into the tumor microenvironment at different times have opposite effects on tumor growth." (PMID 32033341, 2020). "Analysed metabolites were adipokines (adiponectin, leptin, resistine), estradiol, interleukin 6 (IL-6), signalling pathways and tumour anti-oxidative response markers." (PMID 32472095, 2020). "The promoting action of leptin on tumor development is supposed to be mediated by inducing the activation of proangiogenic factors." (PMID 31207998, 2019). "To conclude, this study demonstrates that leptin from obASCs promotes increased human circulating tumor cells and increased metastases in a TNBC PDX model." (PMID 31118047, 2019). "Leptin is a hormone that regulates adipocyte size, as well as the development of certain tumor types." (PMID 31534630, 2019). "We measured gene expression (mRNA levels) of adiponectin, leptin and versican, in adipose tissue explants from normal (hRAN) and tumor (hRAT) kidney." (PMID 31534630, 2019). "It was shown that elevated serum and tissue LEP level is involved in the pathogenesis of lung cancer and tumor metastasis." (PMID 31671654, 2019). "Secondly, the adipose tissue functions as an endocrine organ, which in obese people produces a high level of tumor-promoting hormones, such as leptin and estrogen, and a low level of the tumor suppressor hormone, adiponectin." (PMID 31661891, 2019). "The present study demonstrates the expression of leptin and LepR and their involvement in tumor progression." (PMID 30803210, 2019). "IHC staining showed that leptin was highly expressed in epithelial cells and expressed at a slightly lower level in the cytoplasm of tumor stromal cells (mainly CAF)." (PMID 31119158, 2019). "In this review, we focus on the significant role of the gastric leptin signaling in neoplasia and tumorigenesis in stomach in the context of hereditary and diet-induced obesity." (PMID 31141984, 2019). "This evidence implied that leptin actively affects tumor formation and supports cell proliferation and pluripotency for tumorigenesis." (PMID 31141984, 2019). "Ultimately, this study comprehensively exposes the roles performed by miRNAs such as miR-4443, where in this case miR-4443 acts as a tumor-suppressor miRNA in CRC due to leptin/insulin signaling." (PMID 31007685, 2019). "CSCs play crucial roles in tumor initiation, metastasis and therapeutic resistance and the involvement of leptin in CSC survival has also been proposed in other studies." (PMID 30634494, 2019). "HGSOC ascites are a pro-inflammatory tumor environment that contains a variety of cytokines, chemokines and growth factors including leptin, hepatocyte growth factor (HGF), IL-6, and CCL18." (PMID 31039761, 2019). "Conversely, studies have suggested that high expression of leptin and its receptors in tumours possibly indicate poor prognosis." (PMID 30510663, 2018).
tumor (continued). "Leptin has been shown to act as a growth factor in colonic epithelial cells, promoting tumor cell proliferation and migration and suppressing apoptosis." (PMID 30379922, 2018). "Leptin activated the downstream Jak2/STAT3 signaling in LepR(+) tumor cells, which led to enhanced proliferation, survival and migration of tumor cells." (PMID 30013512, 2018). "This implies that leptin, in part, likely plays an important role in tumor growth as well as in the outcome of DTIC therapy." (PMID 29568521, 2018). "In general, acquiring mesenchymal characteristics favors tumour progression and leptin possibly influences this crucial phenomenon." (PMID 30510663, 2018). "Several studies demonstrated that an imbalanced profile of adipokine expression and release, including elevated levels of leptin, visfatin, and reduced adiponectin supports tumor growth and invasion." (PMID 30208657, 2018). "Upregulated leptin can inhibit the apoptosis of tumor tissue through suppressing antiapoptotic pathway mediated by TGFβ." (PMID 31205932, 2018). "The in vivo impact of leptin-over expressing PC cells was tested by orthotopic implantation into athymic nude mice, which led to greater tumor growth and lymph node metastasis." (PMID 30567565, 2018). "We have previously reported that leptin induces Notch expression and signaling in PC cells, which increases tumor progression." (PMID 29719602, 2018). "We identified the adipokine leptin as a means to remodel the metabolic state of tumor infiltrating T cells." (PMID 30400822, 2018). "Several investigators have evaluated the immunoexpression of Ob-R and/or leptin in tumour tissue samples and tried to ascertain any relationships with the disease processes." (PMID 30510663, 2018). "Our results showed that adipocyte-derived IL-6 and leptin stimulate the migration of tumor cells via upregulation of PLOD2 expression." (PMID 30563531, 2018). "While wild-type oncolytic Vaccinia resulted in some tumor regression, leptin-engineered Vaccinia had superior therapeutic efficacy inducing complete regressions in 30% of mice." (PMID 30400822, 2018). "Pro-inflammatory (such as IL-6 and TNF-α) and proliferative (like leptin and insulin) factors are considered as tumor growth favoring molecules." (PMID 29568521, 2018). "In PC tumor cells, leptin binds to both full-length receptor (OBR1) as well as the short form (OBRs) to mediate downstream signaling." (PMID 30567565, 2018). "We measured genetic expression (mRNA levels) of versican, adiponectin and leptin in adipose tissue far away (hRATfT) and near (hRATnT) tumor cells." (PMID 29212223, 2017). "To validate the results obtained from in vitro experiments, we prepared MCF-7 tumor xenografts in BALB/c nude mice and examined the role of ER signaling in leptin-induced autophagy induction and tumor growth." (PMID 29312618, 2017). "This strengthens the importance of PA in obese women in order to alter their ADIPO:LEP ratio and subsequent tumor growth microenvironment." (PMID 28676553, 2017). "The lower levels of ADIPO and higher levels of LEP in obese individuals correlate with a greater incidence of tumor formation." (PMID 28873415, 2017). "Leptin is an adipokine that plays an important role in energy homeostasis and regulates innate and adaptive responses, thereby modulating the tumor microenvironment." (PMID 28399860, 2017). "Specifically, adiponectin (ADIPO) and leptin (LEP) have been shown to elicit growth effects on tumor cells and their levels are altered as adiposity changes." (PMID 28873415, 2017). "We identified that high tumor expression of LEP and LEPR separately showed a trend toward poor survival." (PMID 29212170, 2017). "The results from this study indicated that high tumor stage tends to have high serum and tissue leptin-LepRb levels." (PMID 28316984, 2017). "A second target of Hif1-α signaling, the cytokine Leptin, was dramatically increased in the dysplastic retina transcriptome (∼500-fold) and remained elevated in tumor tissue." (PMID 28192065, 2017).